LINC00511 (long independently transcribed non-coding RNA 511)
Diseases named in the same sentence as LINC00511 in open-access papers (continued):
Sharing a sentence is not in itself a finding about the gene and the disease.
LINC00511 also shares sentences with these, for which no sentence is quoted: tongue squamous cell carcinoma (6 papers); neuroblastoma (4); adenocarcinoma (3); liver cancer (3); prostate carcinoma (3); squamous carcinoma (2); thyroid cancer (2); tongue cancer (2); adrenocortical carcinoma (1); autoimmune disease (1); cardiovascular disorder (1); cervical intraepithelial neoplasia (1); chronic lymphocytic leukaemia (1); colon adenocarcinoma (1); colon cancer (1); COVID-19 (1); cutaneous melanoma (1); dental caries (1); digestive system cancer (1); esophageal squamous cell carcinoma (1); hepatoblastoma (1); Hyperglycemia (1); laryngeal carcinoma (1); lung squamous cell carcinoma (1); lupus erythematosus (1); metastasis (1); oral cancer (1); periodontitis (1); stomach cancer (1); thyroiditis (1).